CCT8L2 (chaperonin containing TCP1 subunit 8 like 2)
Description:
Possible molecular chaperone; assists the folding of proteins upon ATP hydrolysis.
Synonyms: CESK1
Tractability: No criterion of Open Targets' tractability assessment is met for any kind of drug.
Gene: Protein-coding gene on chromosome 22 (16,590,751 to 16,592,810, reverse strand). Ensembl gene ENSG00000198445.
Subcellular location: Cytoplasm
Gene Ontology:
Molecular function: calcium-activated potassium channel activity; monoatomic anion channel activity; ATP binding; ATP-dependent protein folding chaperone
Biological process: protein folding; monoatomic anion transmembrane transport; potassium ion transmembrane transport
Cellular component: chaperonin-containing T-complex; cytoplasm
Genetic constraint (gnomAD): Loss-of-function variants: 29 observed, 31.59 expected, observed/expected ratio (o/e) 0.92, 90% interval 0.68 to 1.25. The upper end of that interval is the gene's LOEUF score, 1.25, which puts it in group 5 of 6, group 1 being the genes least tolerant of losing a copy. Missense variants: 588 observed, 708.19 expected, observed/expected ratio (o/e) 0.83, 90% interval 0.77 to 0.89. Synonymous variants: 254 observed, 295.5 expected, observed/expected ratio (o/e) 0.86, 90% interval 0.77 to 0.95.
Homologues: Orthologues: chimpanzee CCT8L2 (99% identical), macaque CCT8L2 (94% identical), rabbit CCT8L2 (78% identical), pig CCT8L2 (72% identical), dog CCT8L2 (72% identical), guinea pig CCT8L2 (68% identical), mouse Cct8l1 (63% identical), rat Cct8l2 (62% identical). Paralogues in human: CCT8 (31% identical), CCT2 (23% identical), CCT3 (22% identical), CCT4 (22% identical), CCT5 (22% identical), CCT6A (21% identical), CCT6B (21% identical), CCT7 (20% identical), PIKFYVE (19% identical), TCP1 (18% identical), HSPD1 (16% identical), MKKS (16% identical), and 1 more.
Diseases named in the same sentence as CCT8L2 in open-access papers:
CCT8L2 is named in the same sentence as 2 diseases in open-access papers, as found by Europe PMC text mining. Sharing a sentence is not in itself a finding about the gene and the disease.
CCT8L2 shares sentences with these, for which no sentence is quoted: cancer (1 paper); prostate carcinoma (1).